PART1 (prostate androgen-regulated transcript 1)
Diseases named in the same sentence as PART1 in open-access papers (continued):
Sharing a sentence is not in itself a finding about the gene and the disease.
breast carcinoma (10 papers, 2014 to 2025). "Consistent with the in vitro and in vivo data, high PART1 expression was generally associated with worse survival in basal-like breast cancers patients based on median cutoffs for high versus low expression." (PMID 34072264, 2021). "We demonstrate that lncRNA prostate androgen regulated transcript 1 (PART1) is enriched in TNBCs and in Aldefluorhigh CSCs, and is associated with worse outcomes among basal-like breast cancer patients." (PMID 34072264, 2021). "For this reason, we explored phenotypic and functional characteristics of lncRNA PART1 in breast cancer, which has been previously implicated in both oncogenic and tumor suppressive function in other cancer types including prostate, esophageal, lung, colorectal and glioblastoma." (PMID 34072264, 2021). "In breast cancer cells, knockdown of PART1 has led to decreased proliferation, invasion and migration." (PMID 36875771, 2023). "Suppression of miR-4516 has been found to rescue the effects of PART1 knockdown on breast cancer cells." (PMID 36875771, 2023). "Another study in breast cancer cells has shown that PART1 silencing improves the sensitivity of these cells to cisplatin, promotes cell apoptosis, and decreases expression proteins contributing in drug resistance." (PMID 36875771, 2023). "First, PART1 expression in patient tumors is predominately in the TNBC/basal-like subtype and is associated with worse outcomes among basal-like breast cancer patients." (PMID 34072264, 2021). "To assess if PART1 expression followed the same subtype-specific trends in breast cancer cell lines, we analyzed PART1 expression in a 57-breast cancer cell line panel (CCLE dataset, RNA-seq) and in our 24-breast cell line panel by QPCR." (PMID 34072264, 2021). "Herein, we characterize the expression and function of PART1 in breast cancer using multiple “omics” approaches." (PMID 34072264, 2021). "We report its androgen inducibility in breast cancer cell lines; however, based on gene expression analysis of patient tumors and cells, androgen regulation of PART1 appears to have a minimal clinical impact in breast cancer." (PMID 34072264, 2021). "We used the METABRIC, Cell 2015, and PanCancer Atlas breast cancer datasets (extracted via cBioPortal) and KMplotter to assess PART1 expression in different breast cancer subtypes and its association with clinical data." (PMID 34072264, 2021). "This failed to reveal strong correlations between androgen signaling genes and PART1 in breast cancer patient tumors." (PMID 34072264, 2021). "Together this data leads us to conclude that in TNBC/basal-like breast cancer, where PART1 expression is highest and most likely clinically relevant, androgens do not play a major role in inducing PART1 expression." (PMID 34072264, 2021). "To date, there has been limited analysis of the role of PART1 in breast cancer with only one study reporting pro-oncogenic activities associated with the lncRNA in MCF7 and BT20 breast cancer cells." (PMID 34072264, 2021). "Although PART1 is androgen inducible in breast cancer cells, analysis of patient tumors indicates its androgen regulation has minimal clinical impact." (PMID 34072264, 2021). "Additionally, the interaction of miR-4516 and lncRNA PART1 led to a reduced miR-4516 expression and the promotion of breast cancer development." (PMID 38930863, 2024). "Furthermore, PART1 expression is associated with stemness gene expression and CSC markers in breast cancer patient tumors, Aldefluorhigh sorted CSC populations, and mammosphere formation potential." (PMID 34072264, 2021). "This suggests that in the higher AR expressing ER+ breast cancer cell lines cultured in androgen-containing media, PART1 expression may be at least partially dependent on androgen signaling." (PMID 34072264, 2021). "Therefore, PART1 expression can be amplified by the presence of androgenic signaling molecules in AR expressing breast cancer cell lines (e.g., ER+ T47D cells)." (PMID 34072264, 2021).
breast carcinoma (continued). "Further, our use of PART1-specific antisense oligonucleotides suggests that the lncRNA could be targeted in the treatment of breast cancer and targeting of CSCs." (PMID 34072264, 2021). "To assess the potential clinical relevance of PART1/AR signaling in breast cancer, we assessed the correlation of PART1 expression with the androgen signaling gene panel (containing 10 genes, from cBioPortal) across breast cancer subtypes in two breast cancer patient tumor datasets." (PMID 34072264, 2021). "Notably, in the breast cancer cell lines, androgen receptor (AR) is weakly, positively correlated with PART1, whereas in breast cancer patient tumors, AR is significantly negatively correlated with PART1, potentially suggesting a cell culturing-dependent effect." (PMID 34072264, 2021). "Some evidence suggests that PART1 may play a similar oncogenic role in breast cancer." (PMID 34072264, 2021). "Together, these results support the hypothesis that PART1 is oncogenic in breast cancer." (PMID 34072264, 2021). "To clarify the potential role of PART1 in breast cancer, we studied the consequence of its knockdown and inhibition in the TNBC cell lines and a PDX, assessed its expression correlations with breast cancer patient survival, and evaluated its association with CSC populations." (PMID 34072264, 2021). "Knockdown of LncRNA PART1 led to downregulation of cancer-promoting factor MYO5A and suppression of breast cancer metastasis." (PMID 37667251, 2023). "We assessed the co-expression of PART1 with CSC markers and stemness genes in breast cancer patient tumor datasets, and noted significant correlations, especially in the basal-like subtype." (PMID 34072264, 2021). "Additionally, the silencing of the lncRNA PART1 reduced the expression of MMP13, thereby inhibiting the development of breast cancer." (PMID 40243781, 2025). "The targeting of PART1 with antisense oligonucleotides and resulting negative impact on breast cancer cells suggest that PART1 could be targeted in the treatment of TNBC." (PMID 34072264, 2021). "Since the androgen induction response (although significant) is minimal in TNBC cells, and that there is no connection between androgen signaling and PART1 in breast cancer patient tumors, we opted to not use charcoal-stripped FBS and phenol red-free media for the functional assays." (PMID 34072264, 2021).
lung cancer (8 papers, 2014 to 2024). A malignant neoplasm involving the lung. "Long noncoding RNA prostate androgen‐regulated transcript 1 (PART1) was induced in non‐small cell lung cancer (NSCLC) tissues and cells." (PMID 31436388, 2019). "A previous study reported that lncRNA PART1 knocking down could inhibit proliferation, migration, and invasion via inactivating JAK/STAT signalling in non‐small cell lung cancer." (PMID 33094561, 2020).
bladder cancer (7 papers, 2014 to 2024). "It has been demonstrated that down-regulation of lncRNA PART1 blocks cell proliferation and promotes apoptosis in bladder cancer." (PMID 35949302, 2022). "Multiple studies have found that the overexpression of the lncRNA PART1 promoted the infiltration of mononuclear immune cells, prediction to current immune checkpoint gene markers, inhibition of tumor proliferation, promotion of cell apoptosis, and suppression of cell invasion in bladder cancer." (PMID 35223835, 2022). "Downregulated PART1 could suppress proliferation and accelerate apoptosis in bladder cancer." (PMID 34178478, 2021).
ovarian carcinoma (7 papers, 2019 to 2026). A malignant neoplasm originating from the surface ovarian epithelium. "Taken together, lncRNA PART1 targeted miR-512-3p/CHRAC1 axis to increase cisplatin resistance in ovarian cancer." (PMID 36105363, 2022). "A total of 19 lncRNAs significantly related to prognosis of ovarian cancer were obtained using univariate Cox regression analysis, and the 5 prognostic signature lncRNAs GAS5, HCP5, PART1, SNHG11, and SNHG5 were used to establish a risk assessment system." (PMID 31182053, 2019). "LncRNA PART1 was highly expressed in cisplatin-resistant ovarian cancer cells." (PMID 36105363, 2022). "High expression of GJB2, S100A2, SPOCK2, TGM1or EPS8 indicated a poor OS of patients with ovarian cancer, whereas ovarian cancer patients with higher expression of ADAMDEC1, CHEK1, EGFL6, FAM181A, FOXA2, LYPD1, PART1 or XPR1 possessed better OS." (PMID 31794425, 2019). "PART1 can target miR-512-3p and regulate the expression of CHRAC1 in ovarian cancer cells." (PMID 36105363, 2022). "Furthermore, the expression levels of these upstream lncRNAs were detected by GEPIA, and the study demonstrated that only FUT8-AS1, CASC9, LINC00665, LINC01535, PART1 and LINC00511 were upregulated in ovarian cancer compared with normal samples." (PMID 33123295, 2020).
oral squamous cell carcinoma (6 papers, 2019 to 2024). "Among patients with oral squamous cell carcinoma, patients with high lncRNA PART1 expression survived longer than did those with low lncRNA PART1 expression." (PMID 38807207, 2024). "The expression of PART1 in the oral cavity affects the proliferation of oral squamous cell carcinoma and was also speculated to affect dental caries by regulating immunity and oral microbes." (PMID 36597064, 2023). "This may be because PART1 is located on chromosome 5q12, a region that is usually lost in oral squamous cell carcinoma (OSCC) and head and neck squamous cell carcinoma (HNSCC)." (PMID 30755833, 2019).
hepatocellular carcinoma (5 papers, 2019 to 2024). A malignant tumor that arises from hepatocytes. "ShRNA was transfected to determine whether lncRNA PART1 can regulate the biological function of hepatoma cells and establish Hep3B cells stably." (PMID 34484336, 2021).
pancreatic cancer (4 papers, 2021 to 2024). "However, whether PART1 is associated with the malignant progression of pancreatic cancer remains unclear." (PMID 33865422, 2021). "Our findings suggested that PART1 promoted the malignant progression of pancreatic cancer by sponging miR-122." (PMID 33865422, 2021). "PART1 predicts a poor prognosis and promotes the malignant progression of pancreatic cancer by sponging miR-122." (PMID 34335862, 2021). "PART1 was found to serve as a molecular sponge of miR-122, and miR-122 inhibition partially reversed the inhibitory phenotypes of PART1 knockdown on pancreatic cancer cells." (PMID 33865422, 2021). "PART1 knockdown significantly suppressed cell proliferation and invasion abilities of pancreatic cancer but promoted cell apoptosis." (PMID 33865422, 2021). "Based on the highly expressed PART1 in pancreatic cancer, we investigated the role of PART1 in AsPC-1 and BxPC-3 cells with sh_PART1 and sh_NC." (PMID 33865422, 2021). "To better understand the mechanism of PART1 on pancreatic cancer cell apoptosis, we measured the effect of PART1 knockdown on Bcl-2 and Bax protein expression." (PMID 33865422, 2021). "Here, we transfected sh_PART1 into AsPC-1 and BxPC-3 cells and found that silencing of PART1 increased pancreatic cancer cell apoptosis." (PMID 33865422, 2021). "Consistent with their study results, our experiment results showed that PART1 was highly expressed in pancreatic cancer tissues and cell lines." (PMID 33865422, 2021). "Here, to our knowledge, this is the first research that confirmed that PART1 exerted an oncogenic function in the malignant progression of pancreatic cancer via acting as a sponge for miR-122." (PMID 33865422, 2021). "Functional assays showed that PART1 knockdown suppressed pancreatic cancer cell proliferation and invasion abilities in vitro." (PMID 33865422, 2021). "In the current study, we aimed to identify the role and potential mechanism of PART1 in pancreatic cancer." (PMID 33865422, 2021). "The effects of PART1 and miR-122 on pancreatic cancer growth and metastasis in vivo should be identified." (PMID 33865422, 2021). "In this manner, pancreatic cancer patients might benefit from targeting PART1/miR-122 axis as an effective anticancer therapeutic target." (PMID 36803831, 2023). "In order to assess the role of PART1 in pancreatic cancer, we performed qRT-PCR to detect its expression in 45 cases of pancreatic cancer patients, and found that the expression level of PART1 in cancer tissues was higher than that in para-tumor normal tissues (P < 0.01)." (PMID 33865422, 2021). "PART1 promotes the malignant progression of pancreatic cancer by sponging miR-122." (PMID 33865422, 2021). "In our study, we used a synthetic sh_PART1 to target PART1 in pancreatic cancer cells." (PMID 33865422, 2021). "PART1 expression was upregulated in pancreatic cancer tissues and cell lines." (PMID 33865422, 2021). "Therefore, the purpose of this study was to investigate the impacts of PART1 on the proliferation, invasion, and apoptosis of pancreatic cancer cells, as well as elucidate the relevant mechanism of this action." (PMID 33865422, 2021). "We next evaluated whether PART1 expression correlated with the clinical outcomes in patients with pancreatic cancer." (PMID 33865422, 2021). "To understand the mechanism of PART1-regulated pancreatic cancer progression, we searched public bioinformatics database and found PART1 might be a sponge of miR-122." (PMID 33865422, 2021). "Our results verified that PART1 promoted cell proliferation and invasion in pancreatic cancer." (PMID 33865422, 2021). "qRT-PCR was applied to detect PART1 expression in 45 cases of pancreatic cancer patients." (PMID 33865422, 2021). "We further determined whether PART1 inhibition could also impact the apoptosis of pancreatic cancer cells; flow cytometry analysis was performed." (PMID 33865422, 2021).
pancreatic cancer (continued). "Besides, among these pancreatic cancer cells, AsPC-1 and BxPC-3 cells had a higher PART1 expression than Panc-1 and SW1990 cells and were chosen for further experiments." (PMID 33865422, 2021). "The PART1/miR-122 axis might be a promising target for anticancer therapy in patients with pancreatic cancer." (PMID 33865422, 2021). "Collectively, we deduced that PART1 could promote pancreatic cancer progression; its mechanism may be related to act as a sponge of miR-122." (PMID 33865422, 2021). "Thus, PART1/miR-122 axis might be a novel therapeutic target for pancreatic cancer treatment." (PMID 33865422, 2021). "Compared with HPDE6c7 cell line, all pancreatic cancer cell lines (AsPC-1, Panc-1, SW1990, and BxPC-3) showed increased PART1 expression (P < 0.05)." (PMID 33865422, 2021). "Up to now, there was no report about the role of PART1 in pancreatic cancer." (PMID 33865422, 2021).
gastric cancer (3 papers, 2014 to 2023). A primary or metastatic malignant neoplasm involving the stomach. "PART1 has been shown to restrain aggressive gastric cancer via decreasing expression of PDGFB through PLZF-mediated recruitment of EZH2." (PMID 36875771, 2023). "This study found that PWAR6, LINC00641, SNHG14, and PART1 are markedly downregulated and involved in ferroptosis of gastric cancer." (PMID 36418919, 2022).
liver cancer (3 papers, 2021 to 2022). An epithelial or non-epithelial malignant neoplasm that arises from the liver. "The clinical results showed that PART1 is significantly overexpressed in liver cancer, thereby indicating that PART1 is unrelated to gender, age, and metastasis of liver cancer but related to tumour size, TNM stage, and BCLC stage." (PMID 34484336, 2021). "The lncRNA PART1 in the serum of liver cancer patients and cell lines were significantly upregulated in the present study." (PMID 34484336, 2021). "Hence, liver cancer can be inhibited by suppressing lncRNA PART1 and miR-3529-3p expression on the basis of the blocking effect of FOXC2 and AKT protein expression." (PMID 34484336, 2021). "qRT-PCR and western blot were used to detect PART1 levels in liver cancer serums and cell lines." (PMID 34484336, 2021). "However, the role of PART1 in liver cancer remains unverified." (PMID 34484336, 2021). "Therefore, the present study aimed to investigate the potential role of lncRNA PART1 and its expression pattern in regulating the occurrence and development of liver cancer through miR-3529-3p by targeting the FOXC2-mediated Akt signalling pathway in Hep3B cells." (PMID 34484336, 2021). "Dual-luciferase reporter assays showed that PART1 can sponge miR-3529-3p, which targets FOXC2 in liver cancer cells." (PMID 34484336, 2021). "Hence, PART1 may be a potential tumour marker for the occurrence and development of liver cancer." (PMID 34484336, 2021). "Overall, these data suggested that the downregulation of PART1 can inhibit the proliferation and differentiation of Hep3B cells by targeting the hsa-miR-3529-3p/FOXC2 axis and thus hinder the occurrence and development of liver cancer." (PMID 34484336, 2021). "However, studies on the regulation of PART1 expression and its mechanism in liver cancer are lacking." (PMID 34484336, 2021).
tongue squamous cell carcinoma (3 papers, 2021 to 2024). A squamous cell carcinoma that arises from the tongue. "Moreover, high lncRNA PART1 level has been reported to be linked to good prognosis in patients with tongue squamous cell carcinoma (TSCC)." (PMID 37476905, 2023). "In tongue squamous cell carcinoma tissues and cell lines, lncRNA PART1 was found to be expressed at low levels, while miR-503-5p was highly expressed." (PMID 38807207, 2024). "Further studies revealed that lncRNA PART1 could play a tumour suppressive role in tongue squamous cell carcinoma by targeting miR-503-5p." (PMID 38807207, 2024). "LncRNA PART1 has been demonstrated to be downregulated in tongue squamous cell carcinoma tissues and cells, which could inhibit cell proliferation, invasiveness, and migration via sponging miR-503-5p." (PMID 37476905, 2023).
esophageal cancer (2 papers, 2022 to 2024). A primary or metastatic malignant neoplasm involving the esophagus. "Prostate an-drogen regulated transcript 1 (PART1) is upregulated in gefitinib-resistant esophageal cancer cells and is associated with adverse effects of gefitinib treatment." (PMID 35241975, 2022). "The experimental knockout of PART1 can promote the death of gefitinib-resistant esophageal cancer cells and reduce the resistance of ESCC to gefitinib." (PMID 35241975, 2022).
intervertebral disc degeneration (2 papers, 2021 to 2023). "PART1 is alos involved in the pathogenesis of intervertebral disc degeneration via regulation of the miR-93/MMP2 axis as well as miR-190a-3p expression." (PMID 36875771, 2023). "On the other hand, PART1 has been found to be up-regulated in nucleus pulposus samples of patients with intervertebral disc degeneration." (PMID 36875771, 2023). "The upregulation of lncRNA PART1 expression in the central nucleus pulposus tissue of patients with intervertebral disc degeneration can promote the intervertebral disc degeneration in nucleus pulposus cells by inhibiting the miR-93/MMP2 pathway." (PMID 34484336, 2021).
lymph node metastasis (2 papers, 2021 to 2023). "However, PART1 expression was not related to lymph node metastasis; the possible explanation might be caused by the small size of the samples." (PMID 33865422, 2021).
osteoarthritis (2 papers, 2019 to 2023). A noninflammatory degenerative joint disease occurring chiefly in older persons, characterized by degeneration of the articular cartilage, hypertrophy of bone at the margins and changes in the synovial membrane. "LncRNA PART1 impacted miR-373–3p/SOX4 axis and affected proliferation and apoptosis of chondrocytes as well as ECM degradation in osteoarthritis." (PMID 37779916, 2023). "LncRNA PART1 sponged miR-590–3p and regulated TGFBR2/Smad3, resulting in regulation of viability and apoptosis of chondrocytes in osteoarthritis." (PMID 37779916, 2023).
cervical squamous cell carcinoma (1 paper, 2023). A squamous cell carcinoma arising from the cervical epithelium. "Moreover, PART1 is down-regulated in cervical squamous cell carcinoma tissues." (PMID 36875771, 2023).